BAHCC1 (BAH domain and coiled-coil containing 1)
Synonyms: BAHD2; KIAA1447
Tractability: PROTAC: ubiquitination databases record sites on it.
Gene: Protein-coding gene on chromosome 17 (81,395,457 to 81,466,331, forward strand). Ensembl gene ENSG00000266074.
Subcellular location (Human Protein Atlas): Nucleoli
Gene Ontology:
Molecular function: chromatin binding
Genetic constraint (gnomAD): Loss-of-function variants: 3 observed, 1.03 expected, observed/expected ratio (o/e) 2.92. That is too few expected variants to judge how well the gene tolerates losing a copy. Missense variants: 130 observed, 62.71 expected, observed/expected ratio (o/e) 2.07. Synonymous variants: 58 observed, 32.44 expected, observed/expected ratio (o/e) 1.79, 90% interval 1.42 to 1.97.
Homologues: Orthologues: chimpanzee BAHCC1 (98% identical), macaque BAHCC1 (96% identical), dog BAHCC1 (82% identical), guinea pig BAHCC1 (82% identical), mouse Bahcc1 (82% identical), rat Bahcc1 (81% identical), pig BAHCC1 (81% identical), tropical clawed frog bahcc1 (54% identical), zebrafish bahcc1b (41% identical), zebrafish bahcc1a (40% identical), Drosophila melanogaster wge (15% identical). Paralogues in human: TNRC18 (32% identical), BAHD1 (6% identical).
Diseases named in the same sentence as BAHCC1 in open-access papers:
BAHCC1 is named in the same sentence as 11 diseases in open-access papers, as found by Europe PMC text mining. Sharing a sentence is not in itself a finding about the gene and the disease. The quoted sentences say what the papers report.
leukemia (2 papers, 2017 to 2024). A malignant (clonal) hematologic disorder, involving hematopoietic stem cells and characterized by the presence of primitive or atypical myeloid or lymphoid cells in the bone marrow and the blood. "In leukemia, the depletion of BAHCC1 leads to the inhibition of oncogenesis." (PMID 39150915, 2024).
acute leukemia (1 paper, 2024). A clonal (malignant) hematopoietic disorder with an acute onset, affecting the bone marrow and the peripheral blood. "BAHCC1 is extensively overexpressed in various subtypes of human acute leukemia and plays a vital role in the growth of malignant cells in animals and cell lines." (PMID 39150915, 2024).
breast carcinoma (1 paper, 2024). "Based on the results of this study, the BAHCC1 ranked as the second significant mRNA in lymph node metastasis of breast cancer samples." (PMID 39150915, 2024). "Our results show that GDF5, BAHCC1, LCN2, FGF14-AS2, and IDH2 are among the top five most effective mRNAs involved in lymph node metastasis of breast cancer based on their SHAP values." (PMID 39150915, 2024). "The mechanism by which the BAHCC1 is involved in lymph node metastasis has not been defined in breast cancer and our results suggest elucidating its direct role in breast cancer." (PMID 39150915, 2024).
hepatocellular carcinoma (1 paper, 2020). A malignant tumor that arises from hepatocytes. "BAHCC1 is closely related to prognosis in hepatocellular carcinoma." (PMID 32462000, 2020).
liver cancer (1 paper, 2023). An epithelial or non-epithelial malignant neoplasm that arises from the liver. "The following genes were upregulated in liver cancer: CTB-31N19.5 (methyl transferase like 9), BAHCC1 (Bromo Adjacent Homology domain and Coiled-Coil Containing 1), SCUBE1 (Signal Peptide, CUB Domain and EGF Like Domain Containing 1)." (PMID 37744383, 2023).
melanoma (1 paper, 2020). A malignant, usually aggressive tumor composed of atypical, neoplastic melanocytes. "We constructed a 6-gene signature (IQCE, RFX6, GPAA1, BAHCC1, CLEC2B, and AGAP2) as a novel prognostic marker for predicting the survival of melanoma patients." (PMID 32462000, 2020). "In addition, immunohistochemistry analysis demonstrated that IQCE, RFX6, GPAA1, BAHCC1, CLEC2B, and AGAP2 were highly expressed in melanoma tissues compared with normal tissue." (PMID 32462000, 2020). "In order to verify whether IQCE, RFX6, GPAA1, BAHCC1, CLEC2B, and AGAP2 were highly expressed in melanoma tissues as predicted, we experimentally confirmed this by qRT-PCR and immunohistochemical staining using melanoma tissues extracted from 10 patients." (PMID 32462000, 2020).
pituitary tumor (1 paper, 2022). A benign or malignant neoplasm affecting the pituitary gland. "We also found three hypermethylated genes (C7orf50, GNG7, and BAHCC1) involved in tumorigenesis processes and potentially influencing pituitary tumor pathophysiology." (PMID 35432200, 2022). "Further studies are needed to clarify the role and relevance of C7orf50, GNG7, and BAHCC1 genes—which have been found to be methylated—in pituitary tumor biology, oncogenesis, and clinical expression." (PMID 35432200, 2022). "Finally, we found three hypermethylated genes (C7orf50, GNG7, and BAHCC1), involved in tumorigenesis processes, whose role could be related to pituitary tumor pathophysiology." (PMID 35432200, 2022).
tumor (2 papers, 2020 to 2021). "Six characteristic genes (IQCE, RFX6, GPAA1, BAHCC1, CLEC2B, and AGAP2) were selected by random forest feature selection, many of which have been reported to be associated with tumor progression." (PMID 32462000, 2020).
cancer (1 paper, 2021). A tumor composed of atypical neoplastic, often pleomorphic cells that invade other tissues. "Among the genes downregulated after MLL1 and MLL2 downregulation in our RNA-seq data, we detected three additional transcription factors with known roles in cancer: MYC, PAX2, and BAHCC1 (data not shown)." (PMID 34381018, 2021).
hematological disease (1 paper, 2021). "Genes highlighted here in, such as PRDM16, PER3, NOM1 BAHCC1, ZNF423, SETD7, RPTOR, and others have been implicated in hematological disease development, progression or clinical outcome." (PMID 34200630, 2021).
BAHCC1 also shares sentences with these, for which no sentence is quoted: septal defect (1 paper).